EGFR (epidermal growth factor receptor)
Diseases named in the same sentence as EGFR in open-access papers (continued):
Sharing a sentence is not in itself a finding about the gene and the disease.
tumor (continued). "Many genes in these chromosome lesions, such as EGFR (amp 7p11.2), MET (amp 7q31.2), KRAS (amp 12p12.1), and CACNA2D2 (del 3p21.31), are known to be related to tumor invasion and metastasis." (PMID 28922552, 2017). "Previously, it was already demonstrated that EGFR targeted NIR-tPDT was only successful in EGFR positive cells by using a mixed tumor model that contained both receptor positive and negative cells." (PMID 28415738, 2017). "The epidermal growth factor receptor (EGFR), an ErbB family of receptor tyrosine kinases, is typically known to induce cell proliferation and contributes to transformation of cellular phenotypes by facilitating tumor cell growth and survival." (PMID 29234489, 2017). "Our in vivo study demonstrated that inhibiting EGFR signalling with afatinib was sufficient to slow the growth of FLCN−/− tumours, but did not result in tumour regression." (PMID 28656962, 2017). "It is possible that the discordance between primary tumor and CTC could account for the failure of anti-EGFR therapy in patients with KRASWT tumors, who in fact harbor KRAS mutations in their CTC." (PMID 28674438, 2017). "Because of the heterogeneity in tumor sites and genetic aberrations of HNSCC, however, the identification of biomarkers that would guide anti-EGFR therapy may be challenging." (PMID 29254252, 2017). "In the two present cases, the tumor cells were not eradicated in spite of the marked response to EGFR-TKIs and both our patients relapsed." (PMID 29169381, 2017). "Theoretically, all the EGFR-negative patients or those lacking tumor tissue are eligible for VeriStrat if the oncologist is considering prescribing erlotinib." (PMID 28558785, 2017). "Although RAS mutations are established biomarkers of efficacy to anti-EGFR therapy, anti-EGFR therapy is not effective for all patients with a RAS wild-type tumor." (PMID 29212173, 2017). "On the other hand, in the protein expression profile of SSC-2, the neoplastic proliferation of tumor cells was related to the overexpression of PCNA, MPM2, KRAS, STAT3, EGFR, and bFGF and was supported by the overexpression of the protein translation factors eIF5A, DHS, and DOHH compared to SSC-1." (PMID 28789700, 2017). "Upregulation of c-MET in EGFR TKI gefitinib-resistant HCC827-GR6 xenografts was visualized with a 89Zr-labelled H2 cys-diabody and H2 minibody, with twofold higher uptake observed in resistant tumours." (PMID 28315949, 2017). "We hypothesized that pCLE with C3-Nucview could be used in-vivo to image EGFR-TKI induced apoptosis in preclinical model and on ex-vivo fresh tumor samples at the microscopic level." (PMID 28671975, 2017). "This is understandable given the lack of prospective data to support the claim that the anti-EGFR antibodies indeed perform poorly for right sided tumours." (PMID 28386297, 2017). "The results revealed that ENb-TRAIL has therapeutic efficacy in different tumor entities, which do not respond to either EGFR antagonist or DR agonist monotherapies." (PMID 29213270, 2017). "Thus, in the case of higher PD-L1 expression and low CD8+ TIL post-EGFR-TKI, the duration of tumor control by EGFR-TKI therapy decreased." (PMID 29296194, 2017). "The mechanism of EGFR-TKI resistance will determine the next treatment required, which emphasizes the need to repeat the biopsy and carry out molecular characterization of tumor samples at clinical progression." (PMID 29097733, 2017). "Treatment of mice harboring HSC3/EGFR-GFP tumor xenografts with gefitinib, a small-molecule EGFR tyrosine kinase inhibitor, substantially reduced tumor growth, demonstrating that HSC3/EGFR-GFP tumors require EGFR tyrosine kinase activity to sustain tumorigenesis." (PMID 29268862, 2017). "In addition, epidermal growth factor receptor (EGFR) and mitogen-activated protein kinase (MAPK) have been reported to promote tumor proliferation, migration and invasion." (PMID 28404978, 2017).
tumor (continued). "Of the multiple parameters regarding tumor heterogeneity, 1/COV was the only parameter that was predictive of the EGFR mutation that was not effected or dependent on the metabolic tumor volume diameter." (PMID 28881771, 2017). "The role of residual tumor resection after EGFR-TKI treatment for advanced NSCLC has not been well-established." (PMID 29169381, 2017). "A recent report suggested that the crosstalk between VEGFR and EGFR may be important for tumor growth; that report showed that dual malfunction of the EGFR and VEGFR genes resulted in complete tumor inhibition." (PMID 28388009, 2017). "Our results suggest that the tumour suppressor function of FLCN is, at least in part, due to its ability to inhibit the oncogenic signalling of EGFR, by acting as a GAP protein for Rab7A and therefore modulating the fate of receptor trafficking following endocytosis." (PMID 28656962, 2017). "Our study demonstrates for the first time that the spatial relationship between tumour cells and macrophages, which is not uniform across the tumour bulk, contributes significantly towards the intratumoral, cell-to-cell heterogeneity of EGFR activity." (PMID 28166195, 2017). "Patient #6 was also one of the few who failed to exhibit ERCC1 and EGFR protein modulation after radiation therapy in tumor tissues." (PMID 29160417, 2017). "Reintroduction of wild-type FLCN, but not tumour-associated FLCN mutants, suppresses EGFR signalling in a Rab7A-dependent manner." (PMID 28656962, 2017). "A comparison study of the efficacy and concentrations of the three EGFR TKIs in plasma, tumor tissue, and CSF in an NSCLC brain metastases model has not yet been reported." (PMID 29228726, 2017). "From these results, we concluded that EGFR overexpression was not the only reason for PMPA-induced EGFR activation and tumour growth in LSCC." (PMID 28642617, 2017). "The phosphorylation of EGFR signalling could lead to the activation of PI3K/AKT and RAS/RAF/MEK/MAPK pathways, which could induce tumor angiogenesis." (PMID 28288572, 2017). "The LUX-Lung 3 and 6 trials have shown a significant overall survival benefit in the first-line setting with the EGFR TKI afatinib in patients with the EGFR exon 19 deletion, highlighting the importance of adequate tumour sampling to allow genetic analysis to be undertaken." (PMID 28367333, 2017). "The only established biomarker for the treatment of mCRC patients is tumor RAS mutational status, which is a negative predictive marker for anti-EGFR therapy." (PMID 28368335, 2017). "RHBDD1 and EGFR were correlated regardless of the pathological parameters, including age, gender, tumor size, tumor grade and TNM stage." (PMID 28445956, 2017). "Multivariable logistic regression analysis with inclusion of these parameters revealed that only non-smoker status, peripheral tumor location and low MTV were significant predictors of EGFR mutation." (PMID 28422710, 2017). "Although the TRANS-COG trial investigated the relationship between EGFR gene expression and anti-tumor response of gefitinib, EGFR protein expression was not reported." (PMID 28881608, 2017). "We next assessed the levels of EGFR activity in untreated and Mo-IPQA-treated tumours ex vivo." (PMID 28166195, 2017). "To investigate how intrinsic affinity of the separate arms and format of a bsAb molecule regulates selective targeting under physiological conditions, we selected the human NCI-H358 cell line as a tumor model and the anti-HER2 trastuzumab and anti-EGFR GA201 as model antibodies." (PMID 28067257, 2017). "EGFR TKIs are effective at slowing the proliferation of a tumor cell, but do not lead directly to the death of the cell." (PMID 28611939, 2017). "In vitro, Reg3g upregulated EGFR in DCs, activated heme oxygenase-1 (Hmox1) involved JAK2/STAT3 signaling, raised levels of Th2 cytokines in and suppressed maturation of DCs, and enhanced tumor cell proliferation." (PMID 28880262, 2017).
tumor (continued). "EGFR and MEK1 were found to be over-expressed in the tumor, as compared to healthy lung tissues." (PMID 29285267, 2017). "The survival advantage and long-term duration of effect noticed after few weeks of treatment with nimotuzumab, suggested that inhibition of EGFR signal transduction and tumor proliferation are not the only effector mechanism involved." (PMID 28674498, 2017). "Importantly, dual EGFR and glycolysis inhibition effectively suppressed TNBC cell proliferation and tumor growth." (PMID 28611673, 2017). "This let us assume that the reduced tumor size in the monotherapy group can be attributed only to the killing of high EGFR‐expressing tumor cells but not to a lower proliferation rate of the tumor cells with lower EGFR amount." (PMID 28755527, 2017). "It is estimated that 10% to 50% of patients who underwent biopsy failed to obtain sufficient tumor tissues for EGFR genotyping." (PMID 29340107, 2017). "On the other hand, this let us assume that a monotherapy with HisDianthin‐EGF is not sufficient to kill tumor cells with lower EGFR expression resulting in selective survival of these cells and continuous tumor growth." (PMID 28755527, 2017). "Pembrolizumab is indicated for the first-line treatment of any histological type of metastatic NSCLC if the tumor is highly positive for PD-L1 expression and negative for EGFR and ALK-1 genetic aberrations." (PMID 28653990, 2017). "In particular, our results indicate that erbB-2-positive tumor cells derived from MMTV-erbB-2 transgenic mice were sensitive to lapatinib in vitro and the molecular signaling was specifically inhibited in accordance with erbB-2/EGFR-targeting therapeutics." (PMID 28061785, 2017). "Components of this EGFR/HER2-Ras-Raf-Mek-Erk pathway were co-targeted in the MDA-MB-231 and MDA-MB-468 human TNBC cell lines, and in vitro effects on signaling and cytotoxicity, as well as in vivo effects on xenograft tumor growth and metastasis were assessed." (PMID 29113345, 2017). "This study will determine the best blood EGFR mutation testing method to help clinicians to select NSCLC patients who are most likely to benefit from EGFR TKIs treatment when tumor tissue is absent or insufficient." (PMID 28207548, 2017). "Another study assessed the tumor EGFR IHC data collected during the FLEX study and compared cases with high (IHC score ≥ 200 on a scale of 0-300) versus low (IHC score < 200 on a scale of 0-300) tumor EGFR expression." (PMID 29246028, 2017). "On the other hand, the fusion gene was present in the tumor tissue of patient No.7, but not in the patient’s serum, suggesting that the detection of EGFR-PPARGC1A was not useful as a serum tumor marker." (PMID 28978917, 2017). "Several studies investigated anti-EGFR IgA antibodies; yet, studies of IgA antibodies with other tumor-targeting specificities remain scarce, and no evaluation of a panel of IgA antibodies with multiple targets using a human expression system is available." (PMID 28952521, 2017). "To investigate whether or not EGFR expression was inversely correlated with miR-34a in NSCLC tissues, we evaluated the mRNA expression of EGFR in the 60 primary NSCLC tumors and non-tumor tissues using qRT–PCR." (PMID 28825720, 2017). "Also, some antibodies block the neovasculature formation that accompanies tumor development [anti-vascular endothelium growth factor (VEGF), anti-EGFR, or anti-VEGFR2]." (PMID 28855903, 2017). "We and other groups have demonstrated that decreasing the affinity of HER2 or EGFR CARs could significantly increase the therapeutic index of CAR T cells in vitro and in xenogeneic mouse tumor models." (PMID 28434147, 2017).
tumor (continued). "Despite blocking the downstream signaling pathways by EGFR-TKI, other signaling pathway, such as c-Met, could initiated and facilitate tumor progression." (PMID 29050366, 2017). "To better understand the plasma false-negative results in tumor-tissue EGFR M+ patients, we assessed the quantity and quality of cfDNA from the 93 tumor-tissue EGFR M+ patients (true positives) according to the cfDNA input." (PMID 28052016, 2017). "Likewise, HA-RHAMM interaction enhanced phosphorylation of EGFR, ERK1/2, and STAT3, and these effects were blocked by gefitinib, an inhibitor of EGFR signaling, suggesting that HA-RHAMM signaling uses EGFR to promote tumor cell survival." (PMID 28460475, 2017). "Activated EGFR transmits intracellular signals through many signaling cascades, including RAS/RAF/MAPK, PI3K/AKT, and STAT that regulate multiple cellular processes such as the proliferation, differentiation, migration, invasion, and survival of tumor cells." (PMID 28388589, 2017). "Nevertheless, in all of the mouse tumor models used, EGFR gene-deletion in the cancerous target tissue had no influence on the development of tumors." (PMID 28970798, 2017). "There were some reports on CD47 siRNA that down-regulated CD47 and blocked tumor growth and also other reports demonstrated CD47-SIRP-alpha-independent pathways that blocked tumorigenesis such as interaction with thrombospondin, TSP-1, VEGFR-2 or EGFR." (PMID 29065481, 2017). "MWA of primary tumor sites plus EGFR-TKIs demonstrated no survival advantage compared with EGFR-TKIs alone in advanced NSCLC patients with EGFR sensitive mutations." (PMID 28915624, 2017). "For example, binding to a receptor can block binding of the relevant ligand, such as is the case with cetuximab binding the epidermal growth factor receptor (EGFR), inhibiting soluble EGF binding; thereby reducing proliferation and survival signaling to the tumor." (PMID 29046676, 2017). "Utilizing pharmacological inhibition, genetic loss of function and FRET studies, we show that ENb-TRAIL blocks EGFR signalling via the binding of ENb to EGFR which in turn induces DR5 clustering at the plasma membrane and thereby primes tumor cells to caspase-mediated apoptosis." (PMID 28572590, 2017). "The importance of the Akt pathway in EGFR-TKI resistance was validated in clinical samples from EGFR-mutant NSCLC patients, where phosphorylation of Akt was observed in 60% of tumor samples from patients after progression on EGFR TKIs, but only in 11% of baseline samples." (PMID 28871105, 2017). "We identified few discordant mutations potentially impacting treatment outcome, (for example, EGFR, PTCH1), suggesting that heterogeneous parts of the tumours could respond differently to targeted drugs." (PMID 28186126, 2017). "In addition, the combined use of patritumab with erlotinib, an epidermal growth factor receptor-tyrosine kinase inhibitor (EGFR-TKI), led to increased inhibition of tumor proliferation, compared with patritumab alone." (PMID 28144730, 2017). "EGFR T790M mutation was detected in 30 patients (24.4%) based on ICP analysis of cfDNA, but not in TTG analysis of tumor tissue." (PMID 29290998, 2017). "STAT3 has been characterized as one of the major drivers of GBM, contributing to the maintenance of stemness and a mesenchymal phenotype via the IL-6/glycoprotein 130 (GP130)/STAT3 or EGF receptor (EGFR)/JAK2/STAT3 axis and leading to chemo- and radiation resistance of the tumor." (PMID 29340087, 2017). "Interestingly, following EGF ligand stimulation, EGFR mutant cell line H1975 with L858R showed phosphorylation at Tyr-1045 of EGFR and at Tyr-1248 of HER2 with a similar pattern to that found in tumor tissue." (PMID 28392481, 2017). "On the other hand, the tumor aggressiveness factors, including bone, skin invasion and perineural invasion were not related to EGFR protein overexpression." (PMID 28694429, 2017).
tumor (continued). "While both c-Met and EGFR drive tumor cell growth and invasion, many tumors exhibit EGFR-driven growth independent of c-Met activation." (PMID 28978320, 2017). "Among the more than 200 HSP90 clients are many proteins required for tumor growth, including primary cancer “drivers” such as BCR-ABL1, wildtype ERBB2 and mutant forms of EGFR, ERBB2, FLT3, JAK2 and KIT, as well as critical downstream effectors of these oncoproteins such as AKT1 and RAF1." (PMID 28032595, 2017). "In fact, the PDECX1T0327 model demonstrated rapid tumor regression upon treatment with AZD4547 (12 mg/kg), a selective FGFR inhibitor, suggesting that FGFR may be a stronger driver in this tumor than EGFR." (PMID 28881608, 2017). "After seeing a positive correlation between PHD2 and EGFR in tumor biopsies, we sought to investigate whether PHD2 and EGFR undergo a direct interaction." (PMID 28038470, 2017). "EGFR antagonists could inhibit angiogenic growth factor production (VEGF) and tumor-induced angiogenesis." (PMID 28288572, 2017). "Persistent downstream signaling through the RAS axis can activate multiple processes involved in tumor progression and metastasis without the influence of EGFR and other cell surface receptor kinases." (PMID 28002810, 2017). "p-EGFR reportedly stabilizes snail and slug to trigger EMT and tumor metastasis." (PMID 29069742, 2017). "Accumulated evidence indicates that the combination of EGFR TKI with STAT3 inhibitors could be of benefit and increase the anti-tumor activity of these agents." (PMID 28521301, 2017). "Since EGFR, HER-2 and STAT3 were known as important proto-oncogenes in gastric tumourigenesis, MEG2 might be an effective tumour suppressor in GC." (PMID 28747184, 2017). "IFN-γ+ cells decreased, whereas Foxp3+ cells increased in the tumours composed of lnc-EGFR, but not lnc-EGFRΔR1, -transduced CD4+ T cells." (PMID 28541302, 2017). "Wang and colleagues reported that ~ 20–30% of NSCLC patients have no objective tumor regression on initial EGFR TKI treatment due to intrinsic or primary resistance to EGFR TKIs." (PMID 29090407, 2017). "Western blot analysis revealed a decrease in EGFR phosphorylation both in responder and non-responder tumor samples in the drug treatment arms compared with the control, confirming the pharmacodynamic effect as expected in the explant setting." (PMID 28473715, 2017). "Due to increasing research on molecular tumor markers and NSCLC-driven genes, rapid development of the EGFR targeted therapy, also known as EGFR tyrosine kinase inhibitors (EGFR-TKIs), could effectively control NSCLC progression." (PMID 29254184, 2017). "Of the 3,661 patients with stage IV NSCLC without known EGFR or ALK genomic tumor aberrations or NSCLC NOS histology, 2,904 (79%) patients had at least one record of first-line chemotherapy." (PMID 28644837, 2017). "Two lines of evidence suggest that the anti-tumor activity of MEDI3622 is independent of EGFR activation in this panel of CRC models." (PMID 29029414, 2017). "Since CDK4/6 inhibitors re-sensitize PDX tumors to HER2-targeted therapies and delay tumor recurrence in vivo, CDK4/6 inhibitors may also re-sensitize resistant HER2+ human BRCs to EGFR/HER2 inhibition." (PMID 28533703, 2017). "Hh and AXL pathways are known to play an important role in EGFR resistance through EMT; in one resistant tumor we found that Hh and AXL are concomitantly strongly activated, suggesting that further studies are needed to investigate the interplay between different resistance signaling." (PMID 28416737, 2017). "Although the result was statistically insignificant, tumor cells with EGFR gene amplification carried a higher propensity for lymph node metastasis." (PMID 28854970, 2017).